CHCHD10 (coiled-coil-helix-coiled-coil-helix domain containing 10)
Description:
May be involved in the maintenance of mitochondrial organization and mitochondrial cristae structure.
Synonyms: C22orf16; N27C7-4; MIX17A; FTDALS2; IMMD; SMAJ
Tractability: PROTAC: its protein half-life has been measured.
Gene: Protein-coding gene on chromosome 22 (23,765,834 to 23,767,982, reverse strand). Ensembl gene ENSG00000250479.
Subcellular location: Mitochondrion intermembrane space
Subcellular location (Human Protein Atlas): Mitochondria
Pathways (Reactome):
Protein localization: Mitochondrial protein import
Gene Ontology:
Molecular function: protein binding
Biological process: inner mitochondrial membrane organization; mitochondrion organization; mitochondrial membrane organization
Cellular component: MICOS complex; mitochondrial intermembrane space; mitochondrion; nucleus
Genetic constraint (gnomAD): Loss-of-function variants: 10 observed, 10.89 expected, observed/expected ratio (o/e) 0.92, 90% interval 0.56 to 1.54. The upper end of that interval is the gene's LOEUF score, 1.54, which puts it in group 6 of 6, group 1 being the genes least tolerant of losing a copy. Missense variants: 172 observed, 139.2 expected, observed/expected ratio (o/e) 1.24, 90% interval 1.09 to 1.4. Synonymous variants: 72 observed, 62.94 expected, observed/expected ratio (o/e) 1.14, 90% interval 0.94 to 1.39.
Gene-disease validity (ClinGen):
ClinGen rates the evidence that CHCHD10 causes each of these diseases.
mitochondrial disease (autosomal dominant): Definitive.
frontotemporal dementia and/or amyotrophic lateral sclerosis 2 (autosomal dominant): Moderate.
Homologues: Orthologues: chimpanzee CHCHD10 (99% identical), macaque CHCHD10 (95% identical), guinea pig CHCHD10 (94% identical), pig CHCHD10 (91% identical), rat Chchd10 (87% identical), mouse Chchd10 (85% identical), dog CHCHD10 (82% identical), zebrafish chchd10 (68% identical), tropical clawed frog chchd10 (64% identical), Caenorhabditis elegans har-1 (49% identical), Drosophila melanogaster CG31007 (46% identical). Paralogues in human: CHCHD2 (58% identical).
Diseases named in the same sentence as CHCHD10 in open-access papers:
CHCHD10 is named in the same sentence as 49 diseases in open-access papers, as found by Europe PMC text mining. Sharing a sentence is not in itself a finding about the gene and the disease. The quoted sentences say what the papers report.
amyotrophic lateral sclerosis (46 papers, 2016 to 2026). Amyotrophic lateral sclerosis (ALS) is a neurodegenerative disease characterized by progressive muscular paralysis reflecting degeneration of motor neurons in the primary motor cortex, corticospinal tracts, brainstem and spinal cord. "Mutations in CHCHD2 and CHCHD10 contribute to multiple types of neurodegenerative disorders including amyotrophic lateral sclerosis, Parkinson's disease, and frontotemporal dementia, but have not been observed to be lost in aging." (PMID 41496579, 2026). "Variants in the mammalian MICOS subunit Mic14 (also known as CHCHD10) have been linked to amyotrophic lateral sclerosis and frontotemporal dementia, indicating the importance of this protein." (PMID 40094392, 2025). "CHCHD10 has been associated with a wide range of diseases including amyotrophic lateral sclerosis (ALS), frontotemporal dementia (FTD), Charcot-Marie Tooth disease, cerebellar ataxia, and mitochondrial myopathy." (PMID 37239850, 2023). "CHCHD10 variants have been identified in cases with frontotemporal dementia‐amyotrophic lateral sclerosis (FTD‐ALS; MIM: 615903)." (PMID 32749073, 2020). "The stimulation of mitochondrial import of the pathogenic mutant CHCHD10 was recently proposed as a possible therapeutic strategy for amyotrophic lateral sclerosis." (PMID 30885959, 2019). "In recent years, mutations of CHCHD2 and CHCHD10 are widely linked to a series of neurodegenerative diseases, including Parkinson's disease, amyotrophic lateral sclerosis and frontotemporal lobe dementia 12-14." (PMID 31839816, 2019). "Recently, mutations of the genes for mitochondrial twin CX9C proteins, CHCHD2 and CHCHD10, were identified as being linked to the pathogenesis of Parkinson’s diseases (PD), amyotrophic lateral sclerosis (ALS) and frontotemporal lobe dementia (FTD)." (PMID 30791515, 2019). "Mutations in CHCHD10 have been recently associated with frontotemporal dementia and amyotrophic lateral sclerosis." (PMID 28585542, 2017). "Knock in mouse models bearing CHCHD10 variants were made and could present the symptoms of the CHCHD10-related disease including mitochondrial myopathy, cardiomyopathy, and amyotrophic lateral sclerosis." (PMID 40556660, 2025). "In human cells, MIA substrates have been linked to neurodegenerative diseases such as CHCHD10 (coiled-coil-helix-coiled-coil-helix domain containing 10) in amyotrophic lateral sclerosis and CHCHD2 (coiled-coil-helix-coiled-coil-helix domain containing 2) in Parkinson’s Disease." (PMID 38256258, 2024). "Mutations in CHCHD10 gene are also associated with neurodegenerative disorders, such as amyotrophic lateral sclerosis (ALS), axonal Charcot Marie Tooth disease, and frontotemporal dementia, as well as some forms of autosomal dominantly hereditary mitochondrial disease." (PMID 38020590, 2023). "Second, substrates of the MIA pathway are linked also to primary mitochondrial diseases (such as several mitochondriopathies related to COX deficiencies) and to more common neurodegenerative diseases (such as for example CHCHD2 and CHCHD10, which are linked to amyotrophic lateral sclerosis)." (PMID 33921425, 2021). "Mutations in CHCHD10 can cause amyotrophic lateral sclerosis and frontotemporal dementia." (PMID 33772006, 2021). "CHCHD10 mutations are linked to amyotrophic lateral sclerosis, but their mode of action is unclear." (PMID 29789341, 2018). "Mutations in CHCHD10 are linked to a variety of neurodegenerative diseases, including amyotrophic lateral sclerosis and frontotemporal dementia (ALS-FTD)." (PMID 40452867, 2025). "The mutation of Cys122, identified in amyotrophic lateral sclerosis (ALS) cases, disrupts the mitochondrial import of CHCHD10, emulating the effects observed with the Q108P mutation." (PMID 40430290, 2025).
amyotrophic lateral sclerosis (continued). "Amyotrophic lateral sclerosis (ALS)-linked CHCHD10 is implicated in regulating mitochondrial dynamics and respiratory complex activity, while CHCHD6 (MIC25) participates in the cristae-remodeling MICOS complex." (PMID 39806100, 2025). "CHCHD10 encodes a mitochondrial protein that plays a role in cristae morphology and oxidative phosphorylation, with mutations associated with neurodegenerative diseases, including the spectrum of amyotrophic lateral sclerosis and frontotemporal dementia (ALS-FTD)." (PMID 40452868, 2025). "Mutations in coiled-coil-helix-coiled-coil-helix domain containing 10 (CHCHD10) have been identified as a genetic cause of amyotrophic lateral sclerosis and/or frontotemporal dementia(ALS-FTD)." (PMID 39315251, 2024). "Mutations in coiled-coil-helix-coiled-coil-helix domain containing 10 (CHCHD10) can cause amyotrophic lateral sclerosis and frontotemporal dementia (ALS-FTD)." (PMID 33772006, 2021). "Mutations of coiled-coil-helix-coiled-coil-helix domain containing 2 (CHCHD2) and 10 (CHCHD10) have been found to be linked to Parkinson’s disease (PD), amyotrophic lateral sclerosis (ALS), and/or frontotemporal lobe dementia (FTD)." (PMID 30791515, 2019). "Several mutations in CHCHD10 have been reported in familial and sporadic cases of amyotrophic lateral sclerosis (ALS), frontotemporal dementia (FTD), spinal muscular atrophy, and mitochondrial myopathy, but their mode of action is unclear." (PMID 29789341, 2018). "CHCHD10-related diseases include mtDNA instability disorder, the clinical spectrum of frontotemporal dementia–amyotrophic lateral sclerosis (FTD-ALS), late-onset spinal motor neuropathy (SMAJ), and Charcot–Marie–Tooth disease type 2 (CMT2)." (PMID 40141413, 2025). "Recently discovered to be associated with amyotrophic lateral sclerosis (ALS) and frontotemporal dementia (FTD) in its mutant form, the scientific community would benefit from the availability of validated anti-CHCHD10 antibodies." (PMID 37767023, 2023). "The recent identification of mutations in CHCHD10 implicates mitochondrial dysfunction in the pathogenesis of frontotemporal dementia (FTD) and amyotrophic lateral sclerosis (ALS)." (PMID 29789341, 2018). "CHCHD10‐related diseases include mitochondrial DNA instability disorder, frontotemporal dementia‐amyotrophic lateral sclerosis (FTD‐ALS) clinical spectrum, late‐onset spinal motor neuropathy (SMAJ), and Charcot–Marie–Tooth disease type 2 (CMT2)." (PMID 26666268, 2016). "Mutations in CHCHD10, a gene coding for a mitochondrial intermembrane space protein, are associated with Frontotemporal dementia (FTD)-Amyotrophic lateral sclerosis (ALS) spectrum disorders, which are pathologically characterized by cytoplasmic inclusions containing TDP-43." (PMID 35787294, 2022). "Much like MNRR1, CHCHD10 is associated with various neurodegenerative diseases: spinal muscular atrophy (Jokela type) (SMAJ), amyotrophic lateral sclerosis (ALS) and/or frontotemporal dementia (FTD), lower motor neuron syndrome, and autosomal dominant mitochondrial myopathy." (PMID 33498264, 2021). "The dysfunction of another protein in this family, CHCHD10, emerged recently as a relevant factor in neurodegenerative diseases, such as amyotrophic lateral sclerosis (ALS) and ALS-frontotemporal dementia (ALS-FTLD), among other neurodegenerative diseases." (PMID 37686461, 2023). "Some patients have received amyotrophic lateral sclerosis (ALS) or Charcot-Marie-Tooth (CMT) neuropathy as initial diagnoses, but a gene test of a single heterozygous variant, c.197G>Tp.G66V, in coiled-coil-helix-coiled-coil-helix domain containing 10 (CHCHD10), sets the diagnosis of SMAJ." (PMID 35250809, 2022). "Therefore, in pure forms of amyotrophic lateral sclerosis it is not necessarily associated with CHCHD10 mutations." (PMID 32858900, 2020).
amyotrophic lateral sclerosis (continued). "The association of FTD with MND in this family led us and others to sequence CHCHD10 in cohorts of patients with frontotemporal dementia‐amyotrophic lateral sclerosis (FTD‐ALS) or with pure familial or sporadic ALS." (PMID 26666268, 2016). "Coiled-coil-helix-coiled-coil-helix domain-containing 10 (CHCHD10) is a nuclear-encoded mitochondrial protein which is primarily mutated in the spectrum of familial and sporadic amyotrophic lateral sclerosis (ALS)–frontotemporal dementia (FTD)." (PMID 38132101, 2023). "CHCHD10 mutations associated with FTD/amyotrophic lateral sclerosis (ALS) have been shown that CHCHD 10 mutations impair ability to bind both OPA1 and mitofilin, and these mutants reduced the molecular weight of endogenous CHCHD10, mitofilin, and OPA1." (PMID 36061599, 2022). "The Coiled Coil-Helix-Coiled-Coil-Helix domain containing 10 (CHCHD10) gene was reported to be a risk gene for FTD and amyotrophic lateral sclerosis in Europe, two novel mutations (63C > T, no amino acid change; 71G > A, p.P24L) were also found in Chinese FTD patients." (PMID 32235595, 2020). "This review reveals protective effects and mechanisms of CHCHD2 and CHCHD10 in neurodegenerative diseases characterized by cognitive and motor deficits, such as frontotemporal dementia (FTD), Lewy body dementia (LBD), Parkinson’s disease (PD) and amyotrophic lateral sclerosis (ALS)." (PMID 36061599, 2022).
frontotemporal dementia (42 papers, 2016 to 2026). Frontotemporal dementia (FTD) comprises a group of neurodegenerative disorders, characterized by progressive changes in behavior, executive dysfunction and language impairment, as a result of degeneration of the medial prefrontal and frontoinsular cortices. "CHCHD2 and CHCHD10, linked to Parkinson's disease and amyotrophic lateral sclerosis-frontotemporal dementia (ALS), respectively, are mitochondrial intermembrane proteins that form a heterodimer." (PMID 39131911, 2024). "As different CHCHD10 mutations cause motor neuron disease or frontotemporal dementia, CHCHD10 is likely important at the presynapse as well." (PMID 37239850, 2023). "We and others have previously shown that ALS and frontotemporal lobar degeneration associated with TDP-43 (FTLD-TDP) patient brains exhibit significant reductions in CHCHD10 levels." (PMID 38132101, 2023). "CHCHD2 mutations are already associated with several neurodegenerative diseases, including frontotemporal dementia and Parkinson’s disease, while CHCHD10 mutations have also been found to cause ALS." (PMID 34660586, 2021). "The known CHCHD10 mutations are usually associated with slow progressing forms of late‐onset motoneuron disease and frontotemporal dementia." (PMID 29789341, 2018). "Another mutation, c.176C>T p.S59L, in the CHCHD10 gene was reported with a different phenotype, frontotemporal dementia (FTD)/ALS with mitochondrial myopathy." (PMID 26999347, 2016). "Notably, according to the OMIM database, CHCHD10 is associated with frontotemporal dementia and/or amyotrophic lateral sclerosis 2 (615911), which encompasses a wide range of neurodegenerative conditions." (PMID 39202416, 2024). "Importantly, mutations of the CHCHD10 gene have been associated with frontotemporal dementia and/or amyotrophic lateral sclerosis-2 (FTD/ALS2), myopathy and spinal muscular atrophy (SMA)." (PMID 35362877, 2022). "Indeed, previous studies have shown that mutations of Chchd10 are associated with several diseases, such as frontotemporal dementia and cerebellar ataxia." (PMID 30690467, 2019). "For instance, mutations in the CHCHD10 gene encoding mitochondrial proteins have been identified in frontotemporal dementia-ALS (FTD-ALS), which supports the importance of mitochondrial defects in motor neuron degeneration." (PMID 36163369, 2022). "Recent research has led to the discovery of a CHCHD10 genetic variation in patients with late-onset frontotemporal dementia (FTD)." (PMID 36061599, 2022). "We described a novel heterozygous CHCHD10 mutation (c.176C>T; p.Ser59Leu) in a large French family with a phenotype including cognitive decline resembling frontotemporal dementia (FTD), motor neuron disease (MND), cerebellar ataxia, and mitochondrial myopathy with multiple mtDNA deletions." (PMID 26666268, 2016). "TDP-43 and FTD/ALS-linked CHCHD10 mutations destabilized OPA1-mitofilin complex, impairing mitochondrial fusion and respiration in brains of human FTLD-TDP (frontotemporal lobar degeneration with TDP-43 inclusions) patients, TDP-43 transgenic mice, and HEK293T cells." (PMID 36158221, 2022). "An overview of recently proposed ALS genes that were identified based on rare genetic variants (TBK1, CHCHD10, TUBA4A, CCNF, MATR3, NEK1, C21orf2, ANXA11, TIA1) and their potential relevance to the genetic etiology of frontotemporal dementia have also been described." (PMID 33805659, 2021). "In line with CHCHD2, CHCHD10 has been verified to be involved in multiple neurological alterations including Parkinson’s disease (PD), frontotemporal dementia (FTD), as well as Alzheimer's disease (AD)." (PMID 37438854, 2023). "However, CHCHD10 mutations appear to be the relatively rare cause of ALS and may be more common in patients diagnosed with frontotemporal dementia." (PMID 34202494, 2021). "Importantly, more severe CHCHD10 variants cause ALS and frontotemporal dementia (FTD) or mitochondrial myopathy." (PMID 35250809, 2022).
Mitochondrial myopathy (16 papers, 2016 to 2025). "An autosomal dominant p.G58R mutation of CHCHD10 was reported in a family, presenting characteristics of mitochondrial myopathy and cardiomyopathy." (PMID 40556660, 2025). "Since the initial identification of the S59L substitution in CHCHD10, additional variants have been identified and suggested as pathogenic mediators of ALS-FTD, SMAJ, and mitochondrial myopathy." (PMID 33772006, 2021). "For MNRR1, there is a greater number of diseases associated with altered protein levels, whereas in the case of CHCHD10, a number of mutations were associated with disease, particularly neurodegenerative diseases, as well as one case of mitochondrial myopathy." (PMID 28685009, 2017). "Therefore, it may be beneficial to study neuromuscular transmission in patients with CHCHD10 mutations, especially those diagnosed with mitochondrial myopathy or motor neuropathy." (PMID 37239850, 2023). "Beyond TDP-43-related spectrum disorders, our mechanistic model may also help to shed light on the diversity of disease phenotypes associated with CHCHD10 mutations, such as mitochondrial myopathy, spinal muscular atrophy (SMA), and Charcot-Marie-Tooth disease type 2 (CMT2)." (PMID 35787294, 2022). "CHCHD10 mutations cause heterogenous disease phenotypes including ALS/FTD, mitochondrial myopathy, and cardiomyopathy." (PMID 38724625, 2024). "CHCHD10 variants have been reported in patients with FTD, ALS, motor neuron disease, spinal motor neuronopathy, Charcot-Marie-Tooth disease type 2, and mitochondrial myopathy." (PMID 36158221, 2022). "CHCHD10 G58R and CHCHD10 G66V were identified in mitochondrial myopathy and late-onset spinal muscular atrophy such as VCP and Matrin 3 (MATR3), which also exhibit clinical pleiotropy, including myopathy." (PMID 33805659, 2021). "CHCHD10 has been identified to be associated with a large spectrum of diseases, including FTD, ALS, AD, cerebellar ataxia, mitochondrial myopathy, late-onset spinal motor neuronopathy, and Charcot-Marie-Tooth disease type 237–40." (PMID 34389718, 2021). "Since then, several mutations in CHCHD10 have been associated with neurodegenerative disorders such as ALS and one was linked to a mitochondrial myopathy." (PMID 28685009, 2017). "Mitochondrial myopathy and mitochondrial DNA (mtDNA) instability were observed in patients with CHCHD10 S59L mutation, but not in patients with CHCHD10 G66V mutation." (PMID 36158221, 2022). "Previous studies have evaluated the prevalence of CHCHD2 and CHCHD10 mutations in Italian mitochondrial myopathy patients without mitochondrial DNA mutations." (PMID 33967741, 2021). "However, the CHCHD10 homozygous P96T substitution was found in 1 sporadic mitochondrial myopathy patient." (PMID 33967741, 2021). "CHCHD10 mutations are associated with a spectrum of familial and sporadic frontotemporal dementia-ALS diseases, Charcot–Marie–Tooth disease type 2, mitochondrial myopathy and spinal muscular atrophy Jokela type." (PMID 31557225, 2019).
Parkinson disease (16 papers, 2016 to 2026). A progressive degenerative disorder of the central nervous system characterized by loss of dopamine producing neurons in the substantia nigra and the presence of Lewy bodies in the substantia nigra and locus coeruleus. "Drosophila models expressing human α-synuclein and human CHCHD2 T61I in a Drosophila ortholog of CHCHD2 and CHCHD10, CG5010 (also known as C2C10H)−/− background reproduced parkinsonism-like phenotypes such as motor disabilities, shortened life span, and α-synuclein aggregation in the brain." (PMID 36158221, 2022).